FGF23 (fibroblast growth factor 23)
Diseases named in the same sentence as FGF23 in open-access papers (continued):
Sharing a sentence is not in itself a finding about the gene and the disease.
acute kidney injury (111 papers, 2008 to 2026). Sudden and sustained deterioration of the kidney function characterized by decreased glomerular filtration rate, increased serum creatinine or oliguria. "A Chinese emergency cohort study showed that serum cystatin C, kidney injury molecule-1, neutrophil gelatinase-associated lipocalin, klotho, and fibroblast growth factor 23 are valuable in the early prediction of sepsis-related acute kidney injury." (PMID 36060071, 2022). "Recently, the association between FGF-23 levels and acute kidney injury (AKI) has also been studied." (PMID 34297744, 2021). "Increased FGF23 is frequently seen in critically-ill patients, and has emerged in recent years as an established risk factor for acute kidney injury in this population." (PMID 30971270, 2019). "It has been reported that high FGF23 levels are associated with thin osteoids and a short osteoid maturation time in children with renal failure on peritoneal dialysis." (PMID 23013306, 2012). "However, FGF23 has limited value in predicting progression of renal failure in CKD or in risk prediction in patients on dialysis." (PMID 32130720, 2020). "We identified other gene products that could potentially account for the associations between elevated circulating FGF23 concentrations renal failure progression and cardiovascular mortality that have been found in clinical association studies." (PMID 22970174, 2012). "Given the complex regulation of FGF23 by inflammation, iron status, phosphate metabolism, and assay characteristics, cross-sectional measurements may be insufficient to capture the dynamic changes associated with acute kidney injury." (PMID 40869274, 2025). "However, it has been described that FGF23 also increases with inflammation, such as surgery-related acute kidney injury, and this could be associated with AKI progression." (PMID 39462348, 2024). "Patients with acute kidney injury (AKI) also display elevated FGF23 levels, which are associated with an increased mortality and risk of progression to CKD." (PMID 38530370, 2024). "Other possible roles of IL-6 are the increase in fibroblast growth factor 23 (FGF23) transcription in acute kidney injury (AKI) and CKD, which is associated with increased morbidity and mortality." (PMID 33670423, 2021). "In patients with acute kidney injury (AKI), FGF23 levels rise rapidly after onset of AKI and are associated with AKI progression and increased mortality." (PMID 30405444, 2018). "In patients with acute kidney injury (AKI), plasma and urinary C-term FGF23 (cFGF23) levels rise rapidly after onset of AKI and are independently associated with AKI progression and adverse outcomes." (PMID 30405444, 2018). "In patients with renal failure, increased levels of FGF23 and phosphorus and decreased levels of Khlotho (FGF23 co-receptor) are connected with increased mortality from cardiovascular disease." (PMID 40636828, 2025). "Several studies have shown that there is a relationship between FGF23 levels and cardiovascular mortality, excluding renal failure." (PMID 40636828, 2025). "In contrast to other MBD-related hormones, FGF23 exhibits elevation not only in CKD but also in acute kidney injury (AKI)." (PMID 38496297, 2024). "A recombinant human erythropoietin activates serum FGF23 in mice with normal kidney function and acute kidney injury." (PMID 35622784, 2022). "Fibroblast growth factor 23 (FGF23) is a bone-derived hormone that is elevated during renal failure." (PMID 35268016, 2022). "A clinical study in patients suffering from acute kidney injury (AKI) found a positive association between sepsis severity and FGF23 serum level, underlining the potentially important role of FG23 as a putative immune-regulatory molecule in sepsis." (PMID 33989306, 2021). "Whether elevated FGF-23 levels are associated with an increased risk for contrast-associated acute kidney injury (CA-AKI) and major adverse cardiovascular events (MACE) in patients undergoing coronary angiography remain uncertain." (PMID 34297744, 2021).
acute kidney injury (continued). "The levels of fibroblast growth factor 23 (FGF23) rapidly increases after acute kidney injury (AKI)." (PMID 33866326, 2021). "The degree of renal failure determines the amount FGF23 and PTH required to excrete an excess of P intake." (PMID 33498560, 2021). "Of note, a recent study has demonstrated that during acute kidney injury, kidney-derived glycerol-3-phosphate, a downstream product of glycolysis, acts on bone cells to stimulate FGF23 production." (PMID 34765890, 2021). "Treatment with 0.2 g kg–1 lanthanum hydroxide decreased serum phosphorus, PTH, and FGF23 levels, and delayed the development of renal failure." (PMID 33928079, 2021). "Fibroblast Growth Factor 23 (FGF23) and Klotho play an essential role in the regulation of mineral metabolism, and both are altered as a consequence of renal failure." (PMID 32188018, 2020). "Lowering serum IS, PCS, and even FGF23, is an essential way to deter the progression of renal failure." (PMID 32070049, 2020). "Second, a recent series of elegant experiments identified glycerol-3-phosphate (G3P), a metabolite involved in glycolysis, as a major FGF23 regulator in the setting of acute kidney injury [21••]." (PMID 32857288, 2020). "The association between FGF23 and death has been previously demonstrated in different patient populations, including CKD, renal transplant recipients, acute kidney injury, chronic heart failure, and in the general population." (PMID 31170159, 2019). "In CKD and renal failure, FGF23 concentrations rise to excrete excess phosphate as a result of diminished renal function, leading to high bone turnover." (PMID 29394885, 2018). "The expression of FGF23 mRNA was found of be increased in the following three rat models of CKD used in this study: HP diet-induced renal failure, partial nephrectomy, and DXR-induced renal failure." (PMID 29518087, 2018). "In pediatric CKD and CKD-T patients, the FGF23 level increase and Klotho level decrease with progressing renal failure, despite well-controlled phosphate levels." (PMID 28795324, 2018). "While our findings in acute injury will also need to be examined in more chronic settings, it is noteworthy that rapid changes in FGF23 have been reported in acute kidney injury (AKI), preceding changes in filtration." (PMID 28611350, 2017). "We have noticed a positive correlation between the biomarkers panel of IL-6, OCN, and FGF-23 and renal failure progression (eGFR) in all CKD groups." (PMID 27667892, 2016). "In models of acute uremia they found an increase in FGF23 levels, which was observed already at one hour after acute kidney injury (AKI)." (PMID 25885328, 2015). "Similar to CKD, FGF23 serum levels increase rapidly in acute kidney injury (AKI) in animals and humans." (PMID 26491212, 2015). "Mean serum levels of FGF23 in patients with renal failure can be elevated 700 fold or more (~20,000 ng/l)." (PMID 26019137, 2015). "We also found that secretion of FGF23 into the circulation is enhanced by renal failure-related Pi hoarding at early stages of CKD." (PMID 24466013, 2014). "This is also in agreement with a recent study demonstrating a pronounced increase in vascular calcification and mortality rate in a rat model of renal failure in which neutralizing FGF23 antibodies were administered." (PMID 23577141, 2013). "These gene products provide a possible mechanistic links between elevated FGF23 and pathways responsible for renal failure progression and cardiovascular diseases." (PMID 22970174, 2012). "The effect of acute kidney injury on various forms of FGF23 was assessed in comparison to CKD." (PMID 40869274, 2025). "However, there is significant ambiguity about causation because these relationships lack a strong “exposure-response” link and are non-specific; there are additional reports of positive correlations between FGF-23 and infection, fractures, acute kidney injury (AKI), and all-cause mortality-16." (PMID 38791250, 2024).
acute kidney injury (continued). "In the renal failure setting, high levels of FGF23 regulate downstream signaling pathways, affecting enzyme activity and ion exchange in the inner ear, damaging cochlear capillaries, leading to cochlear sclerosis, and ultimately affecting normal cochlear function." (PMID 36649363, 2023). "Lowering FGF23/D-serine may provide a new strategy for the pharmacological treatment of hearing impairment complicated by renal failure." (PMID 36649363, 2023). "Acute kidney injury (AKI) is a state of high FGF23 and low Klotho." (PMID 37892163, 2023). "Interestingly, it was recently shown that in a model of acute kidney injury, the kidneys themselves produce glycerol-3-phosphate (G3P), which directly stimulates FGF23 production, exclusively in bone." (PMID 35629904, 2022). "In animals, with renal failure, the increase in the renal load of P is accompanied by a reduction in tubular expression of klotho, which generates resistance to the phosphaturic effect of FGF23." (PMID 33498560, 2021). "Moreover, fibroblast growth factor 23 (FGF23), a phosphaturic factor secreted from bone, increased in renal failure." (PMID 32070049, 2020). "Fibroblast growth factor 23 (FGF23) plays a critical role in renal failure." (PMID 32180373, 2020). "Although it remains an open question whether FGF23 directly contributes to kidney injury, elevated FGF23 levels have been associated with progression of CKD15,16,47 and acute kidney injury." (PMID 33163716, 2020). "Conversely, injection of recombinant FGF23 into normal mice suppresses erythropoiesis, and inhibition of FGF23 signaling alleviates the suppression of erythropoiesis in mice with excessive FGF23 blood levels due to renal failure." (PMID 29892265, 2018). "We conducted experiments in a rat model of DXR-induced renal failure as a third model of CKD to investigate whether FGF23 expression is a common phenomenon in renal tubulointerstitial disorder." (PMID 29518087, 2018). "Specifically, FGF23 is associated with left ventricular hypertrophy (LVH), impaired left ventricular function, endothelial dysfunction, heart failure and progression of renal failure in adult CKD." (PMID 28795324, 2018). "Due to association between the level of FGF23 and renal functional state especially in those with renal failure, measurement of FGF23 level may provide prognostic information." (PMID 28497083, 2017). "This discrepancy could possibly arise from the important role VDR, CaR and FGF-23 play in the maintenance of calcium and phosphorus homeostasis which is strongly perturbed in the model of renal failure." (PMID 21695192, 2011). "Elevated plasma Pi seen in renal failure could increase FGF-23 production, although it is possible that reduced clearance of the peptide might also be responsible." (PMID 18288501, 2008). "For example, administration of GDF15 increased klotho expression and reduced FGF23 levels in an experimental model of acute kidney injury (AKI) through folic acid." (PMID 40563333, 2025). "Regarding acute kidney injury (AKI), several studies indicate that there is a significant increase in FGF23, postulating it as a promising early biomarker of AKI." (PMID 38732094, 2024). "Therefore, in the current study, in the early stage of renal failure, the possible compensatory increase in klotho may decrease the plasma level of FGF23, attenuate its destructive effect on TBS, and modulate the effect of renal failure on TBS." (PMID 37507659, 2023). "In recent years, there have been an increasing number of reports on the role of FGF23 in “acute kidney injury (AKI)”." (PMID 37895007, 2023). "Orphan nuclear estrogen-related receptor-γ (ERR-γ) increases hepatic FGF23 synthesis in acute kidney injury (AKI)." (PMID 35084563, 2022). "In acute kidney injury (AKI), the level of FGF23 will also increase immediately, which shows that certain factors are produced in the kidney to promote the production of FGF23." (PMID 34901023, 2021).
acute kidney injury (continued). "FGF23 rises already within hours after an acute kidney injury (AKI), but also during the development and progression of CKD." (PMID 33416083, 2021). "Elevated total FGF23 levels have previously been shown to be associated with increased risk of death in RTRs, as well as in various other patient groups including postoperative acute kidney injury, nondialysis CKD, and ESRD." (PMID 32512806, 2020). "Pre-clinical data suggest that fibroblast growth factor 23 (FGF23) may contribute to pulmonary pathology, and FGF23 is associated with mortality and morbidity, including acute kidney injury (AKI), in non-ARDS cohorts." (PMID 31487315, 2019). "In the current study, preoperative FGF23 levels were found to serve as an effective biomarker for predicting post-HMII/3 right heart failure, postoperative acute kidney injury requiring dialysis and death." (PMID 40863356, 2025). "The level of circulating FGF23 increases rapidly in the early stage of acute kidney injury (AKI)." (PMID 36416954, 2023). "It was demonstrated that FGF23 rises early in CKD, in advance of other alterations, and in acute kidney injury (AKI)." (PMID 36615023, 2022). "Moreover, in acute kidney injury (AKI), FGF23 has turned out to stimulate cell proliferation promoting regeneration of injured tubules through influencing SDF-1/CXCR4 signaling." (PMID 35011602, 2021). "Hence, sepsis-induced acute kidney injury might render the kidney FGF23 resistant." (PMID 33989306, 2021). "A rise in plasma levels of FGF23 has also been found in acute kidney injury (AKI)." (PMID 33233840, 2020). "However, in patients with acute kidney injury, (AKI), FGF23 can be measured following urine analysis, where these elevations correspond with all-cause mortality." (PMID 31461904, 2019). "However, FGF23 can be measured in urine from patients with acute kidney injury (AKI), where elevations correlate with mortality." (PMID 29770125, 2018). "In an acute kidney injury (AKI) mouse model induced by intraperitoneal folic acid injection, elevated plasma FGF23 levels were demonstrated after 1 h of AKI, independently of PTH and vitamin D signaling and dietary phosphate." (PMID 30200452, 2018). "Recently, it was shown that among patients with acute kidney injury (AKI), FGF-23 concentrations are elevated and associated with negative clinical outcomes." (PMID 28130714, 2017). "However, whether FGF-23 has an analogous role in acute kidney injury is unknown." (PMID 21906363, 2011). "Plasma FGF-23 and intact parathyroid hormone (PTH) levels were measured in 12 patients with acute kidney injury and 8 control subjects." (PMID 21906363, 2011). "The evaluation of FGF23 in patients with HMII/3 may provide essential insights for therapeutic decision making, thus helping to reduce mortality, acute kidney injury and right heart failure in such patients." (PMID 40863356, 2025). "ERRγ regulates hepatic fibroblast growth factor 23 (FGF23), an endocrine hormone primarily secreted by osteocytes and osteoblasts, but also induced in hepatocytes in response to folic acid induced acute kidney injury (FA-AKI) and carbon tetrachloride (CCl4) mediated acute liver injury (CCl4-ALI)." (PMID 38479224, 2024). "FGF23 induction is known to be independent of dietary Pi signals in an FA-acute kidney injury model." (PMID 35428804, 2022). "Attainment of a sufficient decline in renal function, verified when rats were no longer receiving adenine as to avoid confounding by acute kidney injury, was demonstrated at Week 6 by elevated creatinine, phosphate, and FGF‐23." (PMID 33190417, 2020). "Our study investigated the negative effects of renal failure and its relationship with phosphorus, FGF23, PTH, sclerostin, and bone." (PMID 29394885, 2018). "In the acute kidney injury (AKI) setting, FGF-23 elevation may precede creatinine elevation and phosphate metabolism impairment." (PMID 25944976, 2015).
acute kidney injury (continued). "We compared a single preoperative measurement of FGF23 as a prognostic tool with the 18 parameters comprising EuroSCORE II with respect to postoperative mortality, acute kidney injury, non-occlusive mesenteric ischemia, clinical course and long-term outcome." (PMID 25902817, 2015). "We questioned whether serum FGF-23 levels correlated with changes in parameters of bone metabolism when a model included underwent PTX and renal failure animals." (PMID 26186634, 2015). "Notably, serum FGF23 levels were increased by approximately 50-fold in both PTH-KL−/− and wild-type mice with renal failure compared to mice with preserved renal function." (PMID 24348262, 2013). "This may explain the FGF23 resistance in parathyroid glands resulting in increased levels of both FGF23 and PTH in patients with renal failure." (PMID 22742720, 2012). "Correlation of FGF-23, iPTH, and Hcy levels together with other laboratory parameters in CKD HD patients may help us for earlier treatment strategies, try to slow patterns of renal failure, and minimize its impacts on the progression to ESRD." (PMID 40612843, 2025). "The authors of the Chronic Renal Insufficiency Cohort study, who analyzed risk factors for CVD and renal failure progression, demonstrated that the coexistence of DM among patients with CKD was independently related to higher levels of phosphate, PTH, and FGF23 compared with nondiabetic individuals." (PMID 35736431, 2022). "They showed that pre-treatment with recombinant FGF23 impaired acetylcholine (Ach)-induced vasodilatation, which was restored after administration of FGF23 blocking antibodies regardless of the presence of renal failure." (PMID 32130720, 2020). "AKI = acute kidney injury; FGF23 = fibroblast growth factor 23; uIL18 = urine interleukin 18; uNGAL = urine neutrophil gelatinase-associated lipocalin; uKIM1 = urine kidney injury molecule-1; uLFABP = urine liver-type fatty acid-binding protein." (PMID 29633705, 2018). "Fibroblast growth factor 23 (FGF23) and insulin-like growth factor binding protein 7 (IGFBP-7) are suggested to be biomarkers for predicting acute kidney injury (AKI)." (PMID 29907141, 2018). "Therefore, iron metabolism may be a link between FGF23 and RDW in our patients with combined chronic heart and renal failure." (PMID 26079688, 2015). "Interestingly, an association between FGF23 levels, impaired left ventricular (LV) function and atrial fibrillation has been reported in patients with CKD and even in patients without renal failure." (PMID 25902817, 2015). "Moreover, preoperative FGF23 independently predicted postoperative acute kidney injury and non-occlusive mesenteric ischemia comparably to the EuroSCORE II." (PMID 25902817, 2015). "Indeed, rats subjected to parathyroidectomy prior to induction of renal failure did not respond with increased FGF23 levels." (PMID 24348262, 2013). "FGF-23 levels were significantly higher in acute kidney injury cases than in critically ill subjects without acute kidney injury, with a median FGF-23 level of 1948 RU/mL (interquartile range (IQR), 437-4369) in cases compared with 252 RU/mL (IQR, 65-533) in controls (p = 0.01)." (PMID 21906363, 2011). "This study aimed to evaluate the value of serum intact fibroblast growth factor 23 (iFGF23), C-terminal FGF23 (cFGF23), and kidney injury molecule-1 (KIM-1) in predicting acute kidney injury (AKI) onset, severity, and renal function recovery in critically ill patients." (PMID 41152128, 2025). "Furthermore, increased FGF23 has been identified as a post-operative indicator of acute kidney injury and non-occlusive mesenteric ischaemia, suggesting that FGF23 levels may be a potential link between multimorbidity and critical care outcomes." (PMID 36829583, 2023). "Further in vivo research illustrated that during renal failure, Klotho in bone was important in inducing FGF-23 production since long bone-specific Klotho ablation mice failed to increase FGF-23 level." (PMID 39465174, 2024).